Y_RNA (Y RNA )
Gene: Miscellaneous RNA gene on chromosome 6 (41,917,416 to 41,917,526, reverse strand). Ensembl gene ENSG00000207371.
Homologues: Orthologues: chimpanzee Y_RNA (99% identical), macaque Y_RNA (98% identical), zebrafish Y_RNA (59% identical). Paralogues in human: Y_RNA (81% identical), RNY1P16 (79% identical), Y_RNA (79% identical), RNY1 (78% identical), RNY1P5 (78% identical), Y_RNA (78% identical), Y_RNA (77% identical), Y_RNA (76% identical), RNY1P11 (75% identical), RNY1P14 (75% identical), Y_RNA (75% identical), RNY1P8 (74% identical), and 88 more.